GFAP (glial fibrillary acidic protein)
Diseases named in the same sentence as GFAP in open-access papers (continued):
Sharing a sentence is not in itself a finding about the gene and the disease.
glaucoma (continued). "Similar spatial-dependent heterogeneity was found in DBA/2J mouse model of glaucoma, which suggested that astrocyte reactivity (increased density, soma, and GFAP expression) occur in micro-domains in the retina." (PMID 36466782, 2022). "The peptain-treated groups showed slightly lower numbers of activated microglia, and GFAP immunoreactivity, suggesting that peptains are capable of reducing neuroinflammation in SO-induced glaucoma." (PMID 36379926, 2022). "In the ONH, GFAP signal intensity (~ 200% of control on average) and area occupied (~ 190% of control on average) was significantly higher in glaucoma along the whole distance of the ONH." (PMID 35986368, 2022). "The activation of macroglia by increased GFAP expression has been observed in human glaucoma and in animal models of glaucoma." (PMID 35625676, 2022). "In the early stage of OHT/glaucoma, or the peripheral retina of late-stage glaucoma, cell density and GFAP expression of astrocytes are reduced." (PMID 36466782, 2022). "In the glaucomatous retina, there is an increased amount of GFAP immunostaining and macroglia display a hypertrophic morphology, suggesting the existence of retinal gliosis in glaucoma." (PMID 35778750, 2022). "A mixture of nutraceuticals containing vitamin B2, B6, B1, B12, etc. efficiently counteracted ganglion cell degeneration and inflammation (cytokine release, GFAP upregulation, and microglia activation) in two different mouse models of glaucoma." (PMID 34206804, 2021). "While the protein is highly up-regulated in glaucoma patients due to microglia activation, the AABs against GFAP were found to be down-regulated in serum and AH samples of POAG patients in comparison to healthy subjects." (PMID 34943212, 2021). "Another protein profile correlating with the AAB profile in glaucoma patients is the glial fibrillary acidic protein (GFAP), an intermediate filament primarily expressed in the retina in astrocytes and Müller cells." (PMID 34943212, 2021). "The loss of RGC at 6 weeks was judged by axon counts and averaged from 15% loss in GLT1-GFP and CD1 mice to 66% in GFP-GFAP mice (n = 5–7 glaucoma eyes per group, p = 0.0001 for GFAP-GFP mice)." (PMID 32822415, 2020). "An increase in GFAP in glial cells has been demonstrated in both animal and human models of almost all retinal diseases, including glaucoma, retinal ischemia and in age-related macular degeneration." (PMID 33424600, 2020). "In parallel research, we are quantifying the number and orientation of astrocyte processes identified by actin and GFAP labeling in mouse glaucoma." (PMID 32822415, 2020). "Knockout animals presented up-regulation of the glial fibrillary acidic protein in Müller cells and evidence of retinal ganglion cell apoptosis, indicating the existence of gliosis and glaucoma-like retinal damage." (PMID 32422965, 2020). "The glaucoma-related fold increase in intensity (P < 0.001) and coverage (P < 0.001) of the retinal GFAP immunolabeling were significantly lower in GFAP-IκKβ mice than IκKβf/f controls." (PMID 32859212, 2020). "Glial activation, a marker of neurological disorder characterized by increased GFAP expression, is also observed in the retinae of glaucoma patients and various experimental COH models." (PMID 31036934, 2019). "NF-κB p50-deficient mice show age-related glaucoma phenotype such as RGC loss, excavation of optic nerve head, activation of glial cells, and increase in GFAP level." (PMID 29951055, 2018). "A reactive astrogliosis, including an increased GFAP expression, has been reported in different retinal pathologies and animal models of glaucoma." (PMID 28878627, 2017). "There are striking parallels between the autoantibody reactions observed in AD, PD, and glaucoma, such as those against glial fibrillary acidic protein (GFAP), S100, and aldolase." (PMID 27090083, 2016).
glaucoma (continued). "In human glaucomatous eyes and in experimental and hereditary animal models of glaucoma, more intense expression of GFAP in Müller cells has been detected in the retina." (PMID 27294114, 2016). "An intravitreal PEDF transfection in a mouse model of glaucoma (DBA/2J mice) resulted in reduced loss of RGCs and the total nerve fiber layer, delayed vision loss, and reduced GFAP expression in the retina and optic nerve." (PMID 27429974, 2016). "In both the human glaucomatous optic nerve head and the retina of different animal models of glaucoma, greater GFAP expression has been detected." (PMID 27294114, 2016). "AP-2β NCC KO mutants, however, exhibited an upregulation in expression of GFAP in the Müller glia, similar to what has been previously observed in other animal models of glaucoma." (PMID 27483349, 2016). "In several models of glaucoma, astrocytes appear to demonstrate increased GFAP immunoreactivity as well as extracellular matrix remodelling at the ONH." (PMID 25490529, 2015). "Histogram analysis revealed that while some groups of astrocytes exhibited high levels of GFAP expression in retina challenged by glaucoma-related stressors, a majority of the astrocyte population had decreased levels of GFAP expression." (PMID 25133067, 2014). "Even at the mild glaucoma stage, GFAP-positive astroglial cells and Iba-1-positive microglial cells were increased in the bilateral LGN." (PMID 22299044, 2012). "PBR-positive cells were observed in LGN layers receiving input from laser-treated eye at all experimental glaucoma stages including the mild glaucoma stage and their localization coincided with Iba-1 positive microglia and GFAP-positive astrocytes." (PMID 22299044, 2012). "It is known that human glaucoma as well as animal models of elevated intraocular pressure alter GFAP immunoreactivity in the retina." (PMID 22848388, 2012). "In the selection of these genes we avoided those with already well described glaucoma related expression changes, such as GFAP and complement components, and focused instead on less well characterized genes." (PMID 21042562, 2010). "GFAP was upregulated following elevation of IOP, and increased GFAP staining was observed in astrocytes at the optic nerve head; this staining correlated strongly with the severity of glaucoma in POAG patients." (PMID 20216911, 2010). "By western blot, we demonstrated an increase in GFAP protein levels using two different models of retina injury: intravitreal ET-1 injection and the Morrison model of glaucoma." (PMID 18836575, 2008). "In POAG patients, increased GFAP staining was observed in astrocytes at the ONH that correlated strongly with the severity of glaucoma." (PMID 18836575, 2008). "Finally, we carried out a bioinformatic re-analysis of a public glaucoma proteomics dataset to explore the putative mechanism of GFAP mAb regulation within the involved protein molecular network." (PMID 40528237, 2025). "This indicates that GFAP mAb may modulate the pathological protein network of glaucoma, particularly through the key regulators GFAP and Caspase-1." (PMID 40528237, 2025). "Similarly, in glaucoma patients’ GFAP levels (coming from astrocytes and Müller cells trespassing the retina) were increased compared to DR and IRD patients (mainly involving inner or the outer retinal layer, respectively)." (PMID 40141267, 2025). "An upregulation of GFAP in optic nerve and retinal astrocytes has been described in human glaucoma." (PMID 38607034, 2024). "In a rodent glaucoma model with chronic ocular hypertension, hypertrophy of Müller cells was found from the inner limiting membrane to the outer nuclear layer, detected by increased expression of glial fibrillary acidic protein." (PMID 38673589, 2024). "Moreover, TNFAIP3 labelling showed an increase in some glaucoma samples and was localized to RGCs and GFAP-positive astrocytes." (PMID 38502591, 2024).
glaucoma (continued). "However, the expression levels of GS and GFAP showed different tendencies during the process of experimental glaucoma." (PMID 39736512, 2024). "From the immunostaining, increased GFAP expression was identified in the glaucoma retina." (PMID 37175778, 2023). "The downregulation of GFAP-IRI in astrocytes has also been observed in other models of glaucoma." (PMID 35625676, 2022). "In consideration of the well-known involvement of retinal activated microglia, astrocytes and Muller glial cells in glaucoma, we assessed retinal Iba1 and GFAP expression, which were significantly (p < 0.05) increased after I/R injury (3-fold and 5-fold, respectively) compared to control." (PMID 34366858, 2021). "Therefore, we examined the effect of siAMPK on microglia/macrophages (Iba1) and reactive astrocytes (GFAP) at 2 weeks after glaucoma induction." (PMID 34187514, 2021). "This study was focused on “GFAP-expressing astroglia,” because astroglial responses are rapidly produced, broadly manifested, and robustly persisting during the chronic disease period with widespread impacts in glaucoma." (PMID 32859212, 2020). "Besides the protection of neuron structure, our observations through PERG recordings were also supportive of a functional protection against experimental glaucoma in GFAP-IκKβ mice." (PMID 32859212, 2020). "GFAP, the main macroglia protein, was investigated in different glaucoma animal models." (PMID 31952234, 2020). "Similar to the glaucoma model, an intense GFAP staining was seen in 12-month-old h3T-A2 mice suggesting a sustained glial activation in the h3T-A2 mice, which may have subsequently directly/indirectly contributed in RGC death." (PMID 24586745, 2014). "Different types of damage, including glaucoma, induce the expression of GFAP in Müller cells." (PMID 20019879, 2009). "Our results showed that GFAP mAb treatment mitigated glaucomatous neurodegeneration both structurally and functionally in vivo, by modulating astrogliosis and astrocyte-microglia activation to inhibit neuroinflammation in glaucoma, ultimately promoting RGC survival." (PMID 40528237, 2025). "In late-stage glaucoma patients, the ONH astrocytes are activated and characterized by morphologic changes (enlarged soma and thicker cellular processes in the prelaminar region, and round-shape cell body and loss of processes in the LC) and increased GFAP expression." (PMID 36466782, 2022). "Although GFAP can provide astrocyte-specific information when focused on the optic nerve, it is important to highlight that this commonly utilized marker may also be expressed by Müller glia (as well as astrocytes) in the retina, particularly in glaucoma." (PMID 32859212, 2020). "Given that upregulation of GFAP, hypertrophy and increased density are all hallmarks of astrocyte reactivity, these data suggest that astrocyte reactivity may occur in a spatially-dependent manner in retina challenged by glaucoma-related stressors." (PMID 25133067, 2014). "At mild, moderate, and advanced experimental glaucoma stages (classified by histological changes based on the extent of axonal loss), brains were stained with cresyl violet, or antibodies against PBR, Iba-1 (a microglial marker), and GFAP (an activated astrocyte marker)." (PMID 22299044, 2012). "Upregulation of GFAP expression, an indicator of reactive gliosis, has been demonstrated in response to various retinal pathologies including mechanical injury, retinal detachment, diabetic retinopathy, glaucoma, retinal ischemia and photoreceptor degeneration." (PMID 21851605, 2011). "In the genetic glaucoma model, in DBA/2J mice, 1% CoQ10 oral administration reduced GFAP expression, indicating its ability to reduce glial activation." (PMID 40430513, 2025). "Intense GFAP and vimentin staining was observed across the retina and ONH in both controls and glaucoma." (PMID 35986368, 2022).
glaucoma (continued). "In the same model of glaucoma in mice 15 days after the laser treatment, astrocytes with high GFAP-IRI and others with low GFAP-IRI were also observed, which only showed soma and primary processes, fundamentally." (PMID 35625676, 2022). "Consistent with changes in human glaucoma, ONH astrocytes were also activated in old DBA/2J mice, with increased expression of GFAP and Cx43." (PMID 36466782, 2022). "Moreover, the expression levels of many other marker proteins such as GFAP, heat shock protein 27 (Gene name: HSP27), or α-crystallin B chain (Gene name: CRYAB) have been correlated with an elevated intraocular pressure (IOP), one of the main risk factors of glaucoma development." (PMID 31470587, 2019). "On the other hand, antibodies against some of the proteins, like GFAP, enhance RGC survival and are present at lower level in glaucoma patients." (PMID 29951055, 2018). "More recent studies of cross-bred mouse strains that develop spontaneous glaucoma in addition to having GFP-expressing astrocytes have also demonstrated the presence of long, thin, non-GFAP-expressing processes in astrocytes responding to high IOP." (PMID 25490529, 2015). "In addition, interestingly, it has been reported that IOP induced the upregulation of GFAP and major histochompatibility complex class II molecule, as well as of microglial activity in the controlateral control retinas in experimental rodent models of glaucoma induced by laser treatment." (PMID 24337820, 2014). "Some of the autoantibodies found in glaucoma occurred in other neurodegenerative diseases as well, for example MPB in MS or GFAP in AD." (PMID 23451242, 2013). "PBR-positive cells were co-labeled in a portion of the Iba-1-positive microglial cells and GFAP-positive astroglial cells in the LGN at both moderate (monkey #2) and advanced glaucoma (monkey #5) stages." (PMID 22299044, 2012). "Next, we performed Pearson correlation coefficient analysis between PBR and GFAP, Iba-1, LGN degeneration (soma size), or optic nerve axons (a glaucoma severity) in each of five glaucoma monkeys." (PMID 22299044, 2012). "Next, to determine transgenic effects on astroglia-driven neuroinflammation, alterations in morphological and molecular responses of astroglia were analyzed in GFAP/cFLIP, GFAP/cFLIPL, and control mice with or without experimentally induced glaucoma." (PMID 38824526, 2024). "Moreover, in the injured brain and experimental glaucoma model, conditional knockout of STAT3 from astrocytes attenuated the injury-induced reactive phenotype, pro-inflammatory cytokine activation, GFAP up-regulation, and scar formation." (PMID 37511525, 2023). "GFAP signal intensity (183% of control) and area occupied (190% of control) was significantly higher in glaucoma at 2 mm eccentricity but not at 6 mm." (PMID 35986368, 2022). "Similarly, increased levels of GFAP were found in the retinas of primate and rodent eyes with optic nerve transection and IOP elevation, as well as in patients with glaucoma." (PMID 34445296, 2021). "Thus, a common feature of all retinal diseases, including RP, glaucoma, DR, and AMD in both animal models and humans, is the presence of a high level of GFAP in Müller cells." (PMID 26733810, 2015). "Therefore, the downregulation of GFAP expression, mainly in OHT eyes, observed in astrocytes in different glaucoma models, could be related to an altered metabolic capacity and a reduced ability to maintain BRB integrity for these cells." (PMID 35625676, 2022). "Finally, TRPV4 inhibition led to reduced Müller cell reactivity, as well as lower overall levels of GFAP expression, TNF-α release, and RGC apoptosis; these findings implied that TRPV4 activation-mediated inflammatory factors were involved in RGC apoptosis in glaucoma." (PMID 34789280, 2021). "In this same model of glaucoma, but in mice, 15 days after OHT induction, both OHT and normotensive contralateral eyes showed a higher intensity of GFAP immunoreactivity compared to naïve eyes." (PMID 35625676, 2022).
retinal degeneration (63 papers, 2007 to 2025). Degeneration of the retina. "Retinal degeneration triggers the activation of Müller glial cells, which is associated with the expression of glial fibrillary acidic protein (GFAP)." (PMID 40170065, 2025). "Müller cells have similar roles as astrocytes, and GFAP expression in Müller cells is considered an indicator of tissue stress, and have been associated with the retinal degeneration." (PMID 37834856, 2023). "GFAP expression in retinal Müller glia is used as an indicator of tissue stress and has been associated with several models of retinal degeneration." (PMID 34063002, 2021). "Additionally, a positive association has been observed between elevated GFAP expression and retinal degeneration, all attributed to exposure to LED light." (PMID 38004409, 2023). "Together, these findings indicated that retinal development remains intact in Prom1-KO mice until P14, after which an increase in the numbers of GFAP-positive glial cells and apoptotic photoreceptors occurs in association with eye opening and the onset of retinal degeneration." (PMID 34664634, 2021). "Because of the high variability in mutant phenotypes, we occasionally observed severe retinal degeneration as early as 6 months, and those retinas had photoreceptor rosette formation, Müller glial activation (GFAP upregulation), and loss of RGCs, as seen in older mutant retinas." (PMID 27699209, 2016). "Given the elevated expression of Edn2 and Gfap apparent in the retina of Prom1-KO mice, we hypothesized that ET-2, the mature form of the Edn2 product, might induce the GFAP expression apparent in association with retinal degeneration in the Prom1-deficient animals." (PMID 34664634, 2021). "Glial fibrillary acidic protein (GFAP) is an intermediate filament (IF) III protein found in astrocytes and MGCs as an indicator of tissue stress, and it has been associated with retinal degeneration." (PMID 40725471, 2025). "Activation of Müller cells and astrocytes, as indicated by increased expression of GFAP, has been shown in a variety of animal models of retinal degeneration, including TH-induced retinal degeneration." (PMID 40943078, 2025). "Vim plays a structural role in MGCs and, along with GFAP, contributes to mechanical stabilization and hypertrophy of reactive MGCs during retinal degeneration." (PMID 39766850, 2024). "The upregulation of GFAP in Müller cells in the retina has only previously been shown in cases of substantial retina degeneration and thus is likely a marker of potent inflammation/degeneration." (PMID 38983084, 2023). "As gliosis involves macroglia, we investigated their gliotic response to determine the role of S100β and intermediate filaments (IFs) GFAP, vimentin, and nestin during tissue repair in a laser-induced model of retinal degeneration." (PMID 37298126, 2023). "However, the reduced number of rods and over-growth of green cones in the nrl-KO retinas could still cause a slowly progressing retinal degeneration, as validated by the elevated levels of apoptosis of retinal cells and significant up-regulation of GFAP in Müller glia." (PMID 35245286, 2022). "Reactive gliosis, revealed by increased GFAP expression in Müller glia, is a well-described feature of many retinal degenerations." (PMID 35334217, 2022). "As a sign of retinal neurodegeneration, reactive gliosis was assessed using GFAP immunoexpression, upregulated in Müller cells during retinal degeneration." (PMID 35221932, 2022). "It has been reported that reduced GFAP expression increased photoreceptor degeneration 59, while other studies found GFAP activation in Müller cells correlated to retinal degeneration." (PMID 36185611, 2022). "Light-induced gliosis was assessed by studying the evolution of astrocyte alterations during retinal degeneration through immunocytochemical localization of GFAP." (PMID 34205615, 2021).